H19 (H19 imprinted maternally expressed transcript)
Diseases named in the same sentence as H19 in open-access papers (continued):
Sharing a sentence is not in itself a finding about the gene and the disease.
pancreatic cancer (continued). "Similarly, many more lncRNAs are on the way to FDA approval and are going through different phases of clinical trials, e.g., the lncRNA H19 is at the stage of clinical trials for glioblastoma, ovarian, bladder, and pancreatic cancer." (PMID 34885213, 2021). "Given its success as a therapeutic strategy for pancreatic cancer, LncRNA H19 may also serve as potential CAVD therapy." (PMID 30460247, 2018). "In addition, the effects of H19 on cell proliferation and invasiveness in our study were similar to those of H19 promoting pancreatic cancer metastasis." (PMID 27911863, 2017). "In this study, a DNA vector expressing the diphtheria-toxin gene under the control of regulatory sequences of the lncRNA H19 was administered intratumorally in unresectable pancreatic cancer patients, envisaging tumor reduction for further complementary therapies." (PMID 26516918, 2015). "The heterotopic model using PC-1.0 hamster pancreatic carcinoma cells also showed delay in tumor growth after administration of either BC-819 alone or Luc-H19 (control vector) + gemcitabine and further delay when the combination of BC-819 and gemcitabine was used." (PMID 22701803, 2012). "Human pancreatic tumor samples from 49 patients were examined for H19 expression by ISH." (PMID 21052499, 2010). "The presented results lead us to advocate a new DNA-based treatment for pancreatic cancer, inducing cytotoxic effect in cancer cells by intratumoral injection of a naked DNA vector containing the DT-A gene under the control of H19 regulatory sequences for human pancreatic cancer." (PMID 21052499, 2010). "H19 expression was also analyzed on PC.1-0 cells, a hamster pancreatic carcinoma cell line." (PMID 21052499, 2010). "In addition to the association of H19 with let-7, H19 could also correlate with miR-675 or miR194 to modulate EMT, cell proliferation, migration, and metastasis of pancreatic cancer, suggesting its role in the regulation of the EMT pathway." (PMID 34439315, 2021). "In a study, PDAC cells treated with 5-FU or abraxane showed overexpression of H19 compared with non-treated cells, which suggested that H19 may be associated with drug resistance in pancreatic cancer cells." (PMID 33402118, 2021). "Thus, a high expression of lncRNA H19 and APOBEC3G may be considered as novel diagnostic markers in pancreatic cancer and sulforaphane analogues may be suited for the development of new and effective drugs for treatment of PDAC and other tumor entities." (PMID 33669381, 2021). "The present study proposes a successful approach for the treatment of pancreatic cancer combining conventional chemotherapy used nowadays and a DNA-based therapy expressing a toxin under the control of regulatory sequences of a differentially expressed gene, the H19 gene." (PMID 22701803, 2012). "In conclusion, our data provide strong evidence for H19-mediated APOBEC3G expression, which in turn activates TGF-β/Smad2 signaling and thereby contributes to the progression of pancreatic cancer, and this process is inhibited by sulforaphane." (PMID 33669381, 2021). "Herein, the H19/miR-675-3p/SOCS5/STAT3 axis plays an important role in pancreatic cancer cells, which revealed potential targets for the treatment of pancreatic cancer." (PMID 34977037, 2021). "H19 is significantly highly expressed in pancreatic cancer cells and regulates the processes of the migration, invasion, EMT and chemoresistance of pancreatic cancer cells." (PMID 34977037, 2021). "Only 10 (SCAMP1, EMG1, HCP5, TUG1, MAL2, H19, LINC00511, RP11-311C24.1, RP11-400F19.6 and CTC-459F4.3) out of 90 lncRNAs were significantly upregulated in pancreatic cancer samples when compared with normal controls." (PMID 31061236, 2019). "Thus, we believe that H19 may act as a tumor suppressor in pancreatic cancer." (PMID 28212565, 2017).
pancreatic cancer (continued). "For example, we screened the expression of H19 in four pancreatic cancer cell lines and filtrated two cell lines (SW1990 and Bxpc3) which have high expression of H19 while two cell lines (Patu8988 and Panc-1) which have low expression of H19." (PMID 28212565, 2017). "A different study revealed that H19 is overexpressed in PDAC tissues and in primary pancreatic tumors that subsequently metastasize." (PMID 26064090, 2015). "We successfully demonstrated by ISH analysis that the H19 gene is expressed in 65% of the analyzed human pancreatic cancer samples (n = 49), indicating that treatment of human pancreatic cancer with the DTA-H19 is very likely to be effective in this disease." (PMID 21052499, 2010). "In addition to H19, PVT1 has been shown to increase EMT in pancreatic cancer tissue by activating the TGF-β/SMAD signaling pathway and inducing proliferation and metastasis by inhibiting SERPINE1 mRNA binding protein 1 (SERBP1)." (PMID 38559560, 2024). "Currently, there is no direct evidence to confirm the relationship between H19 and pancreatic cancer drug resistance; therefore, further studies are required to explore the relationship between H19 and PDAC drug resistance." (PMID 33402118, 2021). "Moreover, H19 increased the expression of VGF to activate the PI3K/AKT/CREB signaling pathway and promote aggressive phenotypes of pancreatic cancer." (PMID 34421359, 2021). "In a pancreatic cancer cell model, H19 over-expression alone, without triggering by EMT inducers, was sufficient to cause a profound induction of Slug, but not Snail expression, with subsequent ablation of E-cadherin protein level." (PMID 26623562, 2016). "We designed a preclinical study combining gemcitabine treatment and a DNA-based therapy for pancreatic cancer using a non viral vector BC-819 (also known as DTA-H19), expressing the diphtheria toxin A chain under the control of the H19 gene regulatory sequences." (PMID 22701803, 2012). "We propose a DNA-based therapy for pancreatic cancer using a nonviral vector, expressing the diphtheria toxin A chain under the control of the H19 gene regulatory sequences." (PMID 21052499, 2010). "The lncRNA H19 targeting agent BC-819 (H19-DTA) has completed clinical trials in ovarian, bladder, and pancreatic cancers with favorable results, though it has not yet received clinical approval." (PMID 41550841, 2026).
diabetes (49 papers, 2009 to 2025). "The results indicate that the H19 SNP rs3741219 AG (p = 0.030) and AG+GG (p = 0.037) alleles are significantly associated with an increased risk of developing DR in individuals with diabetes onset before the age of 45." (PMID 39898248, 2025). "In conclusion, the presence of the H19 SNP rs3741219 variant is associated with a higher risk of DR development in individuals with diabetes onset before the age of 45." (PMID 39898248, 2025). "In the present study, a significant association was identified between the H19 SNP rs3741219 variant and the risk of DR development in patients with diabetes onset before the age of 45." (PMID 39898248, 2025). "The gene enrichment pathway analysis (GEPA) revealed the involvement of insulin-like growth factor 2 mRNA binding proteins and diabetes pathways associated with the lncRNA H19." (PMID 38616192, 2024). "In this study, we show that the levels of HDAC4-6 are increased in the skeletal muscle during diabetes and this is associated with decreased levels of lncRNA H19." (PMID 35842608, 2022). "We have previously demonstrated in mice that the hyperglycemic intrauterine environment of GDM can increase the risk of diabetes in offspring by altering Igf2/H19 imprinting in islets." (PMID 27888796, 2016). "As a result, the H19 SNP rs3741219 variant may serve as an independent predictor for the development of DR in individuals with diabetes onset before the age of 45." (PMID 39898248, 2025). "Furthermore, the H19 SNP rs3741219 variant is also linked to reduced renal function, particularly in those with early-onset diabetes." (PMID 39898248, 2025). "Notably, decreased GFR was more commonly observed in individuals with diabetes onset before the age of 45 who possessed the H19 SNP rs3741219 variant genotypes." (PMID 39898248, 2025). "However, the H19 SNP rs3741219 variant was associated with an increased risk of DR development in patients with diabetes onset before the age of 45." (PMID 39898248, 2025). "Moreover, H19 is a risk locus for some obesity-related disorders such as diabetes, ischemic stroke and coronary artery disease." (PMID 37326896, 2024). "Diabetes severity has been associated with lower lncRNA H19 expression." (PMID 36428545, 2022). "LncRNA H19 is associated with kidney fibrosis by activating EndMT processes in diabetes." (PMID 34199672, 2021). "After adjusting for potential confounding factors such as sex, age, BMI, diabetes, hyperlipidemia, hypertension, cigarette smoking and alcohol drinking, in the logistic regression model, it was found that H19 expression was significantly associated with ischemic stroke (P = 0.001)." (PMID 33541284, 2021). "In addition to the data showing an association with genetic variance implying that H19 plays a role in diabetes, a screen of RNA expression in livers from diabetic mice revealed that H19 was the most altered lncRNA." (PMID 31590432, 2019). "Therefore, ophthalmic and nephrology referrals may be recommended for individuals with the H19 SNP rs3741219 variant and diabetes onset before 45 years." (PMID 39898248, 2025). "However, the role of H19 in diabetes-associated EndMT remains unclear; indeed, H19 overexpression prevented glucose-induced EndMT by reducing the TGF-β1 levels in DR." (PMID 34095153, 2021). "In an age-based subgroup analysis, GFR was significantly lower in diabetic patients with an onset of diabetes before 45 years and with the H19 SNP rs3741219 AG+GG genotype (p = 0.012)." (PMID 39898248, 2025). "Further studies demonstrated that H19 modulates HE4 expression via miR-140, suggesting a novel H19/miR-140/HE4 regulatory pathway for α-mangostin’s potential therapeutic impact in diabetes mellitus." (PMID 40647096, 2025). "H19 also targets other diabetes-related microRNAs, such as members of the let-7 family, miR-19b and miR-200b, through molecular sponging mechanisms." (PMID 39765830, 2024).
diabetes (continued). "In the hyperglycemic condition of diabetes, expression of lncRNA H19 is downregulated, and the overexpression of the non-coding RNA molecule has been shown to abrogate endothelial-mesenchymal transition related to diabetic retinopathy." (PMID 40176927, 2024). "In diabetes, exposure to high glucose levels reduced H19 expression in neonatal cardiomyocytes and in the myocardium of diabetic rats." (PMID 37762249, 2023). "In the context of diabetes and its complications, Zhuo and colleagues observed that H19 was downregulated in STZ-induced diabetic rat models with cardiomyopathy." (PMID 36290744, 2022). "Here, we present data to show that HDAC6 levels are regulated by the lncRNA H19 in the skeletal muscle during diabetes and this regulation modulates IRS1 levels, thereby exerting effects on insulin signaling." (PMID 35842608, 2022). "The maternally expressed lncRNA, H19 has been extensively studied in the skeletal muscle and its role in the skeletal muscle during diabetes has been identified." (PMID 35842608, 2022). "The present study reveals an interesting aspect of HDAC6 regulation by the lncRNA H19 in the skeletal muscle during diabetes." (PMID 35842608, 2022). "The aim of this study was to assess the diagnostic roles of lncRNA H19 and TUG1 for IBS associated with diabetes and to evaluate their association with clinical and laboratory findings." (PMID 36428545, 2022). "In this study, we sought to explore the epigenetic effects of lncRNA H19 in the skeletal muscle during diabetes." (PMID 35842608, 2022). "This indicates that elevated levels of HDAC6 as seen in skeletal muscle during diabetes are possibly mediated by decreased levels of lncRNA H19." (PMID 35842608, 2022). "In light of the role of MAPK signal pathways in apoptosis, we prove the potential involvement of lncRNA H19/miR-29c/MAPK13 signal pathway in the process of cardiomyocyte apoptosis in diabetes." (PMID 35890121, 2022). "Our work sheds new light on the mechanism of H19 in lipid metabolism and also provides a new candidate therapeutic target for treating diabetes mellitus." (PMID 33115498, 2020). "Despite being downregulated in the retina in diabetes, H19 was shown to control endothelial–mesenchymal transition (EndMT), independent of miR-200b." (PMID 30909482, 2019). "Other work indicated that H19 contributed to the gluconeogenesis observed in diabetes by altering the methylation of hepatocyte nuclear factor 4a (HNF4a), which is another critical transcription factor that regulates key enzymes involved in gluconeogenesis." (PMID 31590432, 2019). "In recent decades, lncRNAs such as ANRIL, H19, MALAT1, Sox2OT, and MEG3 have been implicated in playing important roles in the pathology of diabetes and all are known to associate with the pathology of type 2 diabetes." (PMID 31398847, 2019). "The expression of H19 correlated with that of gluconeogenic enzymes and silencing H19 resulted in an increase in their expression implying that H19 was a key regulator of hepatic gluconeogenesis in diabetes." (PMID 31590432, 2019). "These alterations were further confirmed in vivo, in which the diabetic retinal tissues from the H19 KO animals demonstrated a diabetes-like EndMT phenotype (increased mesenchymal and reduced endothelial markers)." (PMID 30909482, 2019). "These put forth interesting observations on the regulatory role of H19 in altering hepatic physiology during diabetes." (PMID 28814771, 2017). "Our results suggest that decreased hepatic H19 levels during diabetes promote FoxO1 nuclear localization and increase gluconeogenesis." (PMID 28814771, 2017). "This study provides a compelling mechanism for the inheritance of childhood diabetes with H19 as a significant factor." (PMID 28933364, 2017). "To conclude, our results identify H19 as a critical regulator of hepatic gluconeogenesis during diabetes and provide new insights into the roles of lncRNAs in metabolism." (PMID 28814771, 2017).
diabetes (continued). "In this study H19 was found to be involved in the intergenerational transmission of diabetes mellitus (gestational diabetes mellitus) and in the diabetes-associated impairment of islet structure and function." (PMID 25093715, 2014). "In the subgroup of individuals with diabetes onset after the age of 45, none of the H19 SNPs were significantly associated with an increased risk of DR (all p > 0.05)." (PMID 39898248, 2025). "Furthermore, H19 has long been proven to be connected with the phenotypic switch of SMCs64 and diabetes, especially in the regulation of glucose metabolism." (PMID 38616192, 2024). "For instance, the suppression of H19 has been shown to protect endothelial cells from high glucose-induced inflammation and oxidative stress by upregulating miR-29b, which plays a role in glucose balance and insulin secretion, impacting diabetes pathogenesis." (PMID 39765830, 2024). "This research proposes a new mechanism through which HF-MSC-Exo promotes chronic skin wound repair, indicating that lncRNA H19 and exosomes could be a therapeutic strategy for diabetes focal skin defects." (PMID 36787444, 2023). "Therefore, HF-MSC-Exo carrying of overexpressing the lncRNA H19 quicken the process of wound healing in diabetes skin." (PMID 36787444, 2023). "Consequently, these findings suggest that lncRNA H19 holds promise as a potential therapeutic candidate for the repair of skin wounds in individuals afflicted with diabetes." (PMID 37881693, 2023). "Downregulation of cell-free lncRNA H19 was observed in diabetes." (PMID 36428545, 2022). "In this study, we sought to explore if decreased levels of H19 might regulate histone modifications and impair metabolic pathways in the skeletal muscle during diabetes." (PMID 35842608, 2022). "Furthermore, overexpression of H19 decreased levels of diabetes-induced autophagy markers, such as LC3-II, BECN1, and ATG7, in cardiomyocytes." (PMID 34234740, 2021). "Thus, H19 downregulation in diabetes can de-repress epigenetic mechanisms to upregulate DIRAS3 and activate autophagy." (PMID 34234740, 2021). "Recently, long noncoding RNA (LncRNA)-H19, which is significantly decreased in diabetes and may be crucial in triggering angiogenesis, has attracted increasing interest." (PMID 29334272, 2018). "Younger individuals with diabetes tend to experience more rapid progression of DR 42, and the deterioration of renal function may be more pronounced in this group under the influence of the H19 SNP rs3741219 genotype." (PMID 39898248, 2025). "Similarly, ENST00000550337.1 levels may be able to differentiate between pre-diabetes and T2D, and circulating H19 levels seem to discriminate patients with better glycemic control from those with poorly controlled diabetes." (PMID 34299336, 2021). "Thus, we speculated that abnormal insulin regulation in diabetes may also affect the predictive role of plasma H19 for CAD in our study." (PMID 28790415, 2017). "H19 may act differently in different tissues impacting diabetes in a multifaceted fashion." (PMID 28933364, 2017). "In the subgroup of individuals with diabetes onset before the age of 45, GFR was significantly lower in those with the H19 SNP rs3741219 AG+GG genotype compared to those with the AA genotype (72.66 ± 35.19 versus 84.59 ± 34.84, p = 0.012)." (PMID 39898248, 2025). "Our study’s key findings were that H19 significantly enhanced cardiac systolic performance in STZ-induced rats and that H19 administration decreased diabetes-induced myocardial fibrosis and cardiomyocyte death." (PMID 36044268, 2022). "We collected the liver from 8-week-old male mice and found that the relative mRNA levels of IGF2 and H19 were both significantly lower in GDM-F1 male mice, which was consistent with the islet results previously published in Diabetes." (PMID 35432202, 2022).